EGF (epidermal growth factor)
Diseases named in the same sentence as EGF in open-access papers (continued):
Sharing a sentence is not in itself a finding about the gene and the disease.
glioma (continued). "Several cytokines and GFs (interleukin (IL)-6, IL-1, epidermal growth factor (EGF), transforming growth factor (TGF), and stress-inducible protein-1 (STI1)) are released by glioma-associated microglia and macrophages, which aid in tumor proliferation and migration." (PMID 37894287, 2023). "Also, amplification of the epidermal growth factor (EGFR) and loss of phosphatase and tensin homolog (PTEN) can contribute to the malignant phenotype of glioma and the downstream targets, Akt and NF-kB, impact oncogenesis, cell proliferation and apoptosis." (PMID 36302993, 2023). "This indicates that transcriptome changes in the process of glioma NS formation are determined to a greater extent by the initial cell-specific context of gene expression, but strongly modulated by the conditions of cultivation in the presence of bFGF and EGF." (PMID 36231068, 2022). "Therefore, SDF1α, together with EGF and IL-8, are key regulators of cell viability in the glioma–microglia microenvironment, in all cell lines." (PMID 34944779, 2021). "Many studies have reported that high levels of TGF-β, EGF, MMP-2, MMP-9 and IL-10, and low levels of IL-12 can be produced by M2 polarized glioma-associated microglia/macrophages to promotes invasion, proliferation, immune evasion and angiogenesis of glioma." (PMID 34446611, 2021). "In addition, the Dirks group also reported that EGF and bFGF enhanced the survival, proliferation, and sphere size of glioma stem cells." (PMID 32102678, 2020). "Abnormal secretion of epidermal growth factor (EGF) by non-neuronal cells (e.g., glioma-associated microglia) establishes a feedback loop between glioblastoma multiforme (GBM) invasion and a functional disruption of brain tissue." (PMID 32443749, 2020). "EGF was reported to augment the invasiveness of non-glial tumors." (PMID 32443749, 2020). "The addition of EGF and bFGF to the culture medium may increase the survival and proliferation of glioma stem cells and can alter their phenotypic potential toward that of neurons, astrocytes, and oligodendrocytes after differentiation in vitro." (PMID 32102678, 2020). "Contrastingly, overexpression of β1,4-N-acetylglucosaminyltransferase III (MGAT3), which adds β1,4 bisecting branches to N-glycans, appears to inhibit EGFR sensitivity to EGF in glioma cells, thereby reducing cellular response to the proliferative effects of EGF." (PMID 31157165, 2019). "Moreover, the growth factor EGF stimulated glioma cells proliferation partially by enhancing EGR1 expression." (PMID 29246166, 2017). "In addition, microglia produce the epidermal growth factor (EGF) and enhance EGF-signaling pathways in glioma cells." (PMID 28670569, 2017). "EGF could effectively induce degradation of IκBα in glioma cells, but this degradation was completely abolished by ibrutinib pretreatment." (PMID 28946903, 2017). "In 2006, inspired by NSC culture conditions, the Fine lab used serum-free, EGF/FGF-2-supplemented Neurobasal medium to cultivate primary glioma cells and found that these cells remained more similar to the parental tumors than those cultured in serum-containing DMEM medium." (PMID 28978189, 2017). "In glioma, EGF or substance P can activate EGFR, which activates ERK and EGR1 biosynthesis." (PMID 29246166, 2017). "In glioma, EGF mainly promotes glioma cells proliferation through EGFR-MEK-ERK-ELK pathway." (PMID 29246166, 2017). "We also found that high expression EGF can promote the proliferation of glioma cells." (PMID 29246166, 2017). "However, BTK inhibition markedly prevented the EGF-induced nuclear accumulation of p65 in glioma cells." (PMID 28946903, 2017). "Notably, functional loss of tetraspanin CD9 led to a marked increase in EGF-stimulated tumor cell invasion, consistent with recent analyses of CD81 and its associated EWI-2 protein complexes in gliomas." (PMID 26377974, 2015).
glioma (continued). "After reading the titles and abstracts, we removed 58 articles not examining the association between EGF polymorphism and glioma risk, 11 articles not examining EGF +61G/A polymorphism, and 9 articles belong to review and meta-analysis." (PMID 24740103, 2014). "EGF/EGFR signaling dysregulation often occurs in gliomas and plays a key role in gliomagenesis." (PMID 24740103, 2014). "Becuase many studies did not estimate the association between EGF +61G/A polymorphism and the risk of glioma at different grade." (PMID 24740103, 2014). "In current results, the correlativity between EGF +61G/A polymorphism and low grade glioma is not clear." (PMID 24740103, 2014). "EFEMP1 suppressed EGF internalization in both of the glioma cell lines (U251 and G43-SA) examined." (PMID 25594013, 2014). "After reading full texts of the remaining 10 articles regarding the association between the rs4444903 polymorphism on the EGF gene and glioma, one of these was excluded for not providing allele frequencies in glioma grade subgroup needed for OR calculation." (PMID 24740103, 2014). "We further compared EGF +61G/A polymorphism in patients with glioblastoma and Grade I-III glioma accordingly, the stronger association between the EGF +61G/A polymorphism and the malignancy of glioma was found." (PMID 24740103, 2014). "Moreover, glioma cells infiltrate into the surrounding tissues with a very complicated microenvironment, in which many growth factors, including EGF, play important roles in promoting glioma cell invasion." (PMID 24312592, 2013). "In glioma cells TRPC1 has been correlated with EGF-mediated directional migration." (PMID 24204345, 2013). "However, glioma has been reported resistant to EGF inhibitors used clinically, thus alternative strategies against EGF-dependent glioma cell invasion are needed." (PMID 24312592, 2013). "However, knock-down of GSK-3α and 3β by small interfering RNA eliminated the enhancement of cell invasion and over-expressing WT- or S9A-GSK-3β also suppressed glioma cell invasion induced by EGF." (PMID 24312592, 2013). "Gab1, the first of the three mammalian gab genes cloned to date, was originally identified as a Grb2-binding protein from a human glial tumor expression library and found to undergo tyrosine phosphorylation in response to stimulation by epidermal growth factor (EGF) and insulin." (PMID 23431498, 2013). "We next examined whether atypical PKC and MAPK pathways were required in EGF-promoted glioma cell invasion." (PMID 24312592, 2013). "Therefore, both atypical PKC and MAPK pathways were indeed important for EGF-promoted glioma cell invasion." (PMID 24312592, 2013). "We then investigated whether GSK-3 and asymmetric GSK-3β regulation were necessary for EGF-induced glioma cell invasion." (PMID 24312592, 2013). "However, the breakthrough in the understanding of the importance of EGF in glioma biology came through Joseph Schlessinger and collaborators' studies on EGF receptor expression in glioma tissue." (PMID 22512247, 2012). "Moreover, simvastatin blocked the stimulation of glioma cell migration by hyaluronan oligosaccharides or epidermal growth factor (EGF)." (PMID 22253629, 2012). "It is well established that EGF promotes astrocytic and glioma cell migration." (PMID 22570591, 2012). "The genotyping was successful for EGF +61A/G in 672 glioma patients and 693 controls." (PMID 20487573, 2010). "Whether there were association between EGF +61 G/A and grade I and III glioma deserved further study, as well as EGF gene - smoking interaction." (PMID 20487573, 2010). "No study had investigated the association between EGF polymorphism and the risk of glioma under different smoking status." (PMID 20487573, 2010). "Previous study evaluated the influence of EGF+61 G/A to glioma risk, but no consensus had been reached." (PMID 20487573, 2010). "EGFR ligands such as EGF are often overexpressed in gliomas." (PMID 20487573, 2010).
glioma (continued). "Studies on glioma cells following EGF stimulation indicated that hEGR1 may be an important part of the EGF-initiated signalling cascades and showed that hEGR1 gene transcripts and protein were undetectable in the absence of cell stimulation by EGF." (PMID 17311025, 2007). "Since both EGFR activation and forced expression of FABP7 promote glioma cell migration, we examined whether inhibiting the expression of FABP7 can suppress glioma cell migration induced by EGF." (PMID 16623952, 2006). "Macrophages are recruited to the glioma environment to create a supportive stroma for glioma cell proliferation, survival, and migration through immune functions, such as the release of transforming growth factor-β, epidermal growth factor, interleukin (IL)-6, and IL-1β." (PMID 34660294, 2021). "Thus, we have provided insight into the vicious cycle between GBM invasion and the disruption of brain tissue, which depends on the abnormal secretion of the epidermal growth factor (EGF) by non-neuronal cells (e.g., glioma-associated microglia)." (PMID 32443749, 2020). "In addition, EGF prevents NSC differentiation, and EGFR signaling is associated with enhanced cellular proliferation, survival, and infiltration in the adjacent parenchyma, similar to the events observed in high-grade gliomas." (PMID 31482066, 2019). "In the meantime though, while one study reported that in U87 glioma cells EGF induced tyrosine phosphorylation of nuclear β-catenin and increased β-catenin transcription activity, little is known about the intranuclear mechanisms via which β-catenin activity is regulated by EGF–EGFR signaling." (PMID 30177836, 2019). "A subset of surgically obtained gliomas can be processed to genetically stable cell lines by growing tumor spheroids in a similar specialized medium containing basic fibroblast growth factor (bFGF), epidermal growth factor (EGF) and neuronal viability supplement B27." (PMID 28074274, 2017). "Glioma-associated microglia and macrophages release several cytokines and growth factors (interleukin (IL) IL-6, IL-1β, transforming growth factor-β (TGF-β)), epidermal growth factor (EGF), and stress-inducible protein 1 (STI1) that facilitate the tumor proliferation and migration." (PMID 28346397, 2017). "Furthermore, the association between EGF +61G/A polymorphism with the development and grade progress of glioma has not been established." (PMID 24740103, 2014). "It has been shown that EGF could greatly promote glioma cell invasion." (PMID 24312592, 2013). "However, when U373 glioma cells were evaluated using positive controls of epidermal growth factor (EGF) or cholera toxin uptake (known to be affected by filipin treatment), the inhibitory effect of filipin on the level of EGF and cholera toxin staining was observed as expected." (PMID 21838899, 2011). "Its activation, often triggered by tumor-associated microglia and macrophages derived cytokines such as EGF, IL-6, and SDF-1α, promotes a tumor-supportive microenvironment by enhancing glioma cell motility, invadopodia activity, and cell cycle progression." (PMID 40867240, 2025). "In contrast, TUBA1B-low-expressing Glioma cells mainly transmitted signals through the PTN pathway and received signals via the PTN, MK, EGF, and CALCR pathways." (PMID 40094001, 2025). "Microglia-derived cytokines and chemokines, particularly PDGFB, EGF, SDF-1α, IL-6, and IL-8, activate Pyk2, but only PDGFB, EGF, SDF-1α and IL-6 promote Pyk2-related glioma cell invasion and proliferation." (PMID 40867240, 2025). "PDGFB, EGF, and SDF-1α all promoted glioma cell migration in a Pyk2-dependent manner, as their effects were abolished upon Pyk2 knockdown." (PMID 40867240, 2025).
glioma (continued). "In a medium containing the growth factors EGF and FGF-2 instead of serum, glioma cells show increased expression of stemness phenotype markers and can form spheres, just like normal neural stem cells." (PMID 38392188, 2024). "When CAFs are co-cultured with glioma C6 cells, the expression levels of VEGF-A and EGF proteins are significantly elevated, thereby enhancing glioma cell invasiveness, proliferation, and angiogenesis." (PMID 39534084, 2024). "Microglia release factors such as stress-inducible protein 1 (STI1), epidermal growth factor (EGF), or transforming growth factor beta (TGF-β), which increase glioma proliferation, migration, and invasion." (PMID 39851932, 2024). "A number of TAM-secreted factors, including stress-inducible protein 1 (STI1), epidermal growth factor (EGF), TGF-β, and matrix metallopeptidase-2 (MMP-2), have been shown to enhance proliferation and invasiveness of glioma cells." (PMID 38254796, 2024). "Another factor known to stimulate both cell proliferation and migration is the epidermal growth factor (EGF); the overexpression of its receptor (EGFR) characterizes, indeed, high-grade gliomas." (PMID 39194524, 2024). "Several factors, including STI1, EGF, CSF-1, CCL2, IL-6, TGF-β and TGF-β2, are released from TAMs and can promote glioma proliferation and/or migration." (PMID 37705736, 2023). "Another example of boronated PAMAM dendrimer was functionalized with the epidermal growth factor (EGF), since the EGFR gene is found on the cell surface of the majority of high-grade gliomas." (PMID 37631334, 2023). "Consistent with previous studies that showed inhibition of RTK signaling in non-glioma cells upon EMP3 silencing, we observed higher EGF-induced EGFR degradation in our EMP3 KO cells." (PMID 37936247, 2023). "While certain growth factors, such as EGF and FGF, can stimulate glioma cell proliferation, high VEGF expression is crucial for glioma angiogenesis." (PMID 38259287, 2023). "Glioma-associated macrophages have been revealed to express several significant modulators that induce glioma growth and invasion, including IL-1β, TGF-β, IL-6, epidermal growth factor (EGF), and STI1, by modulating the perivascular GICs and glioma cells." (PMID 37012233, 2023). "The use of the PEG3400 linker created a spacer >200 atoms in length between the EGF and the biotin/SA complex and this extended linker removed the steric hindrance of the SA complex on EGF binding to the EGFR on human glial tumor cells." (PMID 35745855, 2022). "As the correlation coefficients (R) between EGF and DDX60 were >0.5 in both CGGA glioma and CGGA GBM database, western blot was then employed to demonstrate the strong association between EGF and DDX60 (P = 0.002, R = 0.56)." (PMID 34178649, 2021). "Inhibitors of PDGFRβ, EGFR, or SDF-1αR (DMPQ, gefitinib, and burixafor, respectively) significantly reduced the stimulatory effect of MCM in all cell lines, confirming the key role of microglia-derived PDGFβ, EGF, and SDF-1α in glioma cell migration." (PMID 34944779, 2021). "Others, such as epidermal growth factor (EGF), stimulate glioblastoma cell invasion, or transforming growth factor-β (TGF-β) that increases the migration of glioma cells." (PMID 34944036, 2021). "Specifically, EGF, PDGFβ, and SDF-1α promote glioma cell invasion by inducing the formation of functional invadopodia and stimulating cell migration." (PMID 34944779, 2021). "Based on these results, we suggest that EGF, IL-6, SDF-1α, and PDGFβ together orchestrate Pyk2 and FAK regulation in glioma cells, leading to cell cycle activation." (PMID 34944779, 2021). "Based on these results, EGF, PDGFα, PDFGβ, IL-6, IL-8, and SDF-1α were selected as candidates for the microglial regulation of Pyk2 and FAK signaling in glioma cells." (PMID 34944779, 2021).
glioma (continued). "TAMs have been shown to release a plethora of factors that stimulate tumor growth and invasion, including TGF-β, IL-1β, IL-6, stress-inducible protein 1 (STI1), and epidermal growth factor (EGF) by acting on GSCs in the perivascular niche and glioma cells." (PMID 33766119, 2021). "Western blot analysis with clinical samples and DDX60 knockdown glioma cells demonstrated that DDX60 protein expression was correlated with PD-L1 (P < 0.0001, R = 0.86) and EGF (P = 0.002, R = 0.56)." (PMID 34178649, 2021). "We identified microglia-derived PDGFβ, EGF, SDF-1α, IL-6, and IL-8 as factors involved in the activation of Pyk2 and FAK signaling in glioma cells." (PMID 34944779, 2021). "EGF and IL-6 together, and to some extent also with SDF-1α and PDGFβ, play a role in enhancing glioma cell mitosis and viability." (PMID 34944779, 2021). "We identified microglia-derived EGF, PDGFβ, SDF-1α, and IL-6 as the primary activators driving Pyk2 and FAK activation in glioma." (PMID 34944779, 2021). "In addition, leukemia inhibitory factor could maintain the stemness of glioma stem cells, and EGF, bFGF, and leukemia inhibitory factor together enable the expansion of neural stem cells in culture and allow them to retain their multipotency for at least 1 year in vitro." (PMID 32102678, 2020). "Studying glioma model, EMT was initiated by growing C6 cells in serum-free stem cell medium (SCM) containing growth factors [epidermal growth factor (EGF), fibroblast growth factor (FGF), Platelet-derived growth factor (PDGF)-alpha-beta]." (PMID 32195174, 2020). "The microglial-released EGF increases tumor invasion by activating its receptors on GBM cells, while CSF-1 secreted by glioma acts as a chemoattractant for TAMs." (PMID 31231208, 2019). "In summary, recruitment and subsequent M2 polarization of GAMs has been shown to be mediated by multiple glioma cell-derived chemoattractants such as MCP-1 (CCL2), SDF-1 (CXCL12), M-CSF (CSF-1), GM-CSF, and EGF." (PMID 29389898, 2018). "We treated glioma cells with the following recombinant ErbB family ligands: EGF, NRG1, and HB-EGF protein." (PMID 29864158, 2018). "While ligands such as EGF, HGF, and PDGF can stimulate glioma invasion, blocking of these signaling pathways by anti-cancer drugs has not been so effective due to signal transduction redundancy in response to these drugs and co-expression of these molecules." (PMID 28166231, 2017). "Although EGF can improve EGR1 expression and promote glioma cells proliferation, many articles proved that high EGR1 expression would inhibit cells growth." (PMID 29246166, 2017). "A number of signalling pathways that include autocrine components, such as TGFalpha/EGF/EGFR, PDGF/PDGFR, HGF/SF and CXCL12/CXCR4 ligand/receptor systems, have been identified in glioma and glioblastoma." (PMID 29149169, 2017). "TSCs of glioma were enriched from U87 and two primary cells (SHG62, and SHG66) using serum-free medium supplemented with growth factors, including bFGF, EGF and B27." (PMID 28388894, 2017). "While glioma cell-derived CSF1 plays a critical role for the differentiation and survival of TAMs, TAM derived EGF may contribute to the high EGFR signaling in the gliomas cells, even in the absence of mutations within the EGFR gene or amplification of this region." (PMID 27385209, 2016). "We expanded GSCs from established glioma LN18 cells and cultures derived from GBM specimens (WG4, L0125 and L0627) in serum-free medium with the growth factors (EGF, bFGF)." (PMID 27934912, 2016). "The first link between EGFR activity and VEGF expression was reported almost 20 years ago when it was shown that two EGFR ligands, EGF and TGFα, stimulated the expression of VEGF in glioma cells and in hyperproliferative keratinocytes." (PMID 27806094, 2016). "Several genes including e.g. F5, LAMA1, ERBB2 or STARD3 seems to be in proximity to genes of the EGF/EGFR signaling cascade, which is known to be important in glioma." (PMID 25537509, 2015).